MTDH (metadherin)
Diseases named in the same sentence as MTDH in open-access papers (continued):
Sharing a sentence is not in itself a finding about the gene and the disease.
cancer (continued). "Overexpression of MTDH, also known as LYRIC, is observed in a variety of cancers and is involved in cancer initiation, proliferation, invasion, metastasis and chemoresistance." (PMID 27755556, 2016). "Currently, many studies on MTDH mainly focus on its expression difference, molecular characterization, signaling pathways, and MTDH impacts in different cancer cells." (PMID 25993398, 2015). "In recent years, functional and clinical evidence significantly support an important function of AEG-1/MTDH in cancer development, including transformation, the evasion of apoptosis, invasion and metastasis." (PMID 25009642, 2014). "Future studies are required to evaluate the correlation between AEG-1/MTDH function and signaling changes and interacting partners in order to highlight novel perspectives for AEG-1/MTDH as a significant target for the clinical treatment of various cancers." (PMID 25009642, 2014). "Based on the molecular targeting of AEG-1/MTDH, novel cancer treatments consist of several possible avenues." (PMID 25009642, 2014). "It is also recognized that MTDH involves in the resistance of chemotherapeutic drugs in many other types of cancer, probably through various signaling pathways including PI3K/AKT, Wnt/b-catenin, and NFκB." (PMID 25417825, 2014). "AEG-1/MTDH presents as an ideal target for the development of the next generation of effective cancer therapeutics." (PMID 25009642, 2014). "Astrocyte elevated gene-1 (AEG-1, also named metadherin [MTDH] or Lyric) has been established as an oncogene in a variety of cancers." (PMID 24941119, 2014). "The results suggested that the expression of the AEG-1/MTDH protein was significantly higher in cancer cell lines with high metastatic potential, such as Sk-HEP-1 and MHCC-97H, than in those with low metastatic potential, such as HepG2 and Huh7." (PMID 25009642, 2014). "Immunoprecipitation of these components followed by mass spectrometry analysis revealed that the ubiquitylated proteins were retained by metadherin (MTDH), an ER-anchored protein with increased expression in several carcinomas." (PMID 25396681, 2014). "AEG-1 mRNA codes for a single pass transmembrane protein, with predicted molecular weight of 64 kDa, identified as a metastasis adhesion protein (metadherin) that enhances migratory capacities of cancer cells." (PMID 22884085, 2012). "Overexpression of MTDH has been observed in carcinomas and has been correlated with poor clinical outcomes." (PMID 21408129, 2011). "But in our study, we found MTDH mainly localized in the cytoplasm of intraductal proliferative lesions and cancer cells, there is very little nuclear staining." (PMID 20565850, 2010). "Tumorigenic potential of MTDH was supported by two observations, elevated expression in subsets of cancer cell lines and promotion of anchorage independent growth of immortalized melanocytes and astrocytes." (PMID 20565850, 2010). "Furthermore, various studies have identified SND1 as a crucial binding partner of MTDH, highlighting its significant role in cancer metastasis and chemoresistance." (PMID 41286067, 2025). "Additionally, observed reductions in protein levels in pathways essential for actin cytoskeleton regulation and integrin-mediated cell adhesion suggest a role for MTDH in enhancing cancer cell motility and invasion." (PMID 41286067, 2025). "MTDH has been reported to regulate glucose metabolism and lipid metabolism in cancer cells." (PMID 41318030, 2025). "Moreover, the authors indicated that reduced miR-30d expression causes activation of the PI3K/Akt pathway by stimulating the MTDH gene, inhibiting apoptosis and increasing the proliferation of cancer cells in MM." (PMID 38473390, 2024). "In cancers, oncogene Ha-ras was suggested to increase the expression of MTDH by PI3K/AKT pathway." (PMID 36348199, 2023). "SND1 and MTDH are known to promote cancer and therapy resistance, but their mechanisms and interactions with other oncogenes remain unclear." (PMID 37973913, 2023).
cancer (continued). "MTDH has been associated with the NF-κB, AKT, and ERK pathways, affecting cancer cell function." (PMID 36902125, 2023). "MTDH has been found to play a role in signaling pathways related to cancer." (PMID 36902125, 2023). "Additionally, the upregulation of MTDH increased the invasion of cancer cells by upregulation of matrix metalloprotease enzymes (MMPs), specifically MMP-2 and MMP-9." (PMID 36902125, 2023). "Both EMT and m6A RNA methylation correlated with MTDH expression in cancers; therefore, we hypothesized a mutual correlation between MTDH, EMT, and m6A RNA methylation." (PMID 34622157, 2021). "Due to the converse expressions of RKIP and MTDH in our data, it is important to determine the molecular mechanism of the correlation between the two proteins in order to understand the regulation of cancer progression." (PMID 33802672, 2021). "Furthermore, qRT-PCR results demonstrated that MTDH mRNA expression in cancer tissues was noticeably higher than that in adjacent tissues (P < 0.001)." (PMID 34552061, 2021). "Although more designed experiments and trials are needed in the future, targeting MTDH may help to overcome immunotherapy resistance in a wide range of cancers." (PMID 34622157, 2021). "Theoretically speaking, the expression of MTDH in cancer would be dysregulated and might impact ICB immunotherapy response for patients with cancer." (PMID 34622157, 2021). "We found that few cancer tissue samples had any genetic alterations (2% of cases) of the MTDH gene." (PMID 33802672, 2021). "We conducted a survival analysis to determine the expression level of MTDH in the cancer tissues, and observed that patients with higher expression of MTDH developed poorer prognosis, while those with lower expression of MTDH had a more satisfactory prognosis (P < 0.001)." (PMID 34552061, 2021). "It has been reported that MTDH is an oncogene in some kinds of cancer." (PMID 34234862, 2021). "However, there is no study to investigate the potential role and mechanisms of MTDH in ICB-treated cancers." (PMID 34622157, 2021). "Dysregulation of miR-497 could affect metadherin expression that results in tumorigenesis and cancer progression." (PMID 34577789, 2021). "MTDH is an oncogene that is overexpressed in many types of malignant tumors." (PMID 34504842, 2021). "A PubMed literature search using AEG-1 or MTDH as a keyword identifies 514 papers, many of which analyzed the clinical significance of AEG-1 overexpression in cancers firmly establishing AEG-1 as a diagnostic/prognostic marker for most common cancers as well as a key determinant of metastasis." (PMID 33671513, 2021). "Given that MTDH mediates the adhesion of cancer cells to lung endothelium, many ways against MTDH were developed to inhibit lung metastasis of BC, e.g., the antibodies reacting to the LHD of MTDH, the multiple tyrosine kinase inhibitor (TKI) SU6668, and DNA vaccines." (PMID 34208889, 2021). "Moreover, MTDH also increased the expression of p-NF-κB and p-p38, executing its function in promoting cancer." (PMID 31978894, 2020). "Importantly, auto-antibodies against the MTDH protein have been detected in cancer patients confirming its immunogenicity and supports MDTH as a potential immunotherapy target." (PMID 31131259, 2019). "We have demonstrated for the first time that MTDH enhances the vulnerability of cancer cells to ferroptosis and may serve as a therapeutic biomarker for future ferroptosis-centered cancer therapy." (PMID 31527591, 2019). "MTDH plays an important role in progression and metastasis of many cancers." (PMID 31131259, 2019). "MTDH is pro-oncogenic factor playing multifaceted and diverse roles in cancer progression." (PMID 31131259, 2019). "Further investigations revealed MTDH expression in various cancer types capable of metastasis." (PMID 31131259, 2019).
cancer (continued). "Given its increased expression in many cancer types it would be important to determine whether MTDH represents a feasible target for cancer therapy, including immune-therapy." (PMID 31131259, 2019). "In summary, the present study demonstrates that MTDH enhances the vulnerability of cancer cells to ferroptosis, and suggests that MTDH may be a therapeutic biomarker for future ferroptosis inducing agents to treat cancer." (PMID 31527591, 2019). "As MTDH promotes a therapy-resistant, mesenchymal-high cell state, we therefore focused on whether MTDH enhances the vulnerability of cancer cells to ferroptosis inducers and the mechanism of the underlying vulnerability." (PMID 31527591, 2019). "Expression of MTDH is increased in many different cancer types." (PMID 31131259, 2019). "Multiple mechanisms converge to promote expression of MTDH in cancers." (PMID 31131259, 2019). "In this review, we summarize data on MTDH function in various cancers." (PMID 31131259, 2019). "We also investigated the potential mechanism of the miRNAs and found that the overexpression of miR-145 and miR-497 inhibited TGF-β-induced EMT in NSCLC cell, and the miRNAs may exert its anti-cancer role by directly targeting an oncogene, MTDH." (PMID 30065618, 2018). "This discrepancy might be due to the fact that the biological function of MTDH in PDAC is different from that in other cancers." (PMID 29029495, 2017). "MTDH is frequently up regulated and related with worse outcomes in cancers." (PMID 29088804, 2017). "Downregulation of these miRNAs enhanced the expression of MTDH in cancer cells." (PMID 27765924, 2016). "Our large cohort study indicated that expression of MTDH was upregulated in cancer tissues." (PMID 27765924, 2016). "Our study provided a preclinical framework for MTDH inhibition derived from MM to other cancers." (PMID 26683226, 2016). "This strongly supported the potential finding that anti-cancer therapy via targeting MTDH in HCC might have great value." (PMID 26287185, 2015). "Recently, accumulating research results have been showing that MTDH could also promote malignant tumor growth." (PMID 26287185, 2015). "MTDH has been observed to be important in conferring drug resistance in cancer treatment." (PMID 25684730, 2015). "MTDH might be a pivotal molecule not only in the progression of cancers but also in relation of cancer, innate immunity and inflammation." (PMID 25993398, 2015). "Multiple mechanisms have been identified to contribute to MTDH overexpression in cancers." (PMID 25333261, 2014). "AEG-1/MTDH is seminal in regulating proliferation, invasion, angiogenesis, metastasis and chemoresistance, as determined by ‘gain-of-function’ and ‘loss-of-function’ studies in human cancer cells and through the analysis of a transgenic mouse model." (PMID 25009642, 2014). "A novel gene that has been identified is AEG-1 [also known as Metadherin (MTDH) and Lysine-rich CEACAM1 co-isolated (LYRIC)], which has emerged as a potentially crucial mediator of malignant tumors, and a key converging point of a complex network of oncogenic signaling pathways." (PMID 25009642, 2014). "AEG-1/MTDH inhibition may be an effective anticancer strategy, considering that AEG-1/MTDH is overexpressed in a variety of cancer types and regulates the fundamental processes of carcinogenesis." (PMID 25009642, 2014). "However, certain controversy exists regarding the localization of the AEG-1/MTDH protein in the nucleus or cytoplasm of cancer cells, and the utility of nuclear or cytoplasmic AEG-1/MTDH to predict the course and prognosis of disease." (PMID 25009642, 2014). "In our present study, we found that MTDH is a molecule linking inflammation and cancer." (PMID 22195048, 2011). "The results provide evidence that MTDH might be a pivotal molecule not only in the progression of cancers but also in relation of cancer, innate immunity and inflammation." (PMID 22195048, 2011).
cancer (continued). "However, it is still unknown whether MTDH S-palmitoylation regulates metabolic homeostasis in cancer cells." (PMID 41318030, 2025). "Further functional analyses of MTDH and the interacting protein SND1 with RNA silencing, as well as targeting their interaction, revealed that disrupting this interaction leads to the dysregulation of several pathways associated with cancer progression and invasion." (PMID 41286067, 2025). "Therefore, targeting MTDH S-palmitoylation to enhance ferroptosis sensitivity may represent a novel cancer therapeutic strategy." (PMID 41318030, 2025). "Interestingly, coexpression of β‐catenin and metadherin could also be detected in malignant ascites originating from other primary cancer types such as gastric and endometrioid cancers." (PMID 35403834, 2022). "Thus, perturbing the MTDH–RKIP relation in human cancer might serve as a target developing effective anticancer therapy." (PMID 33802672, 2021). "Taken together, MTDH may promote immunotherapy resistance by regulating the EMT of the cancer cell." (PMID 34622157, 2021). "Moreover, miR-9-3p had a targeted binding relationship with MTDH, and overexpressed miR-9-3p greatly promoted the toxic effects of Gem on cancer cells and expressions of apoptosis-related proteins, whereas overexpressed MTDH partially reversed such effects of overexpressed miR-9-3p." (PMID 34552061, 2021). "Additionally there is new evidence suggesting that functional inhibition of MTDH function could be the novel approach to treat cancer." (PMID 31131259, 2019). "Our data suggest that MTDH may have great potential in controlling enormous miRNA regulatory networks to regulate tumorigenesis, and further confirm that MTDH is a promising target for cancer prevention and therapy." (PMID 28107197, 2017). "Thus, it appears that overexpression of MTDH in cancer cells enhances its aggressiveness." (PMID 27765924, 2016). "Many studies demonstrated that MTDH might play important roles in the pathogenesis, progression, apoptosis regulation, angiogenesis, invasion, metastasis, and overall patient survival in diverse human cancers." (PMID 25333261, 2014). "Collectively, these findings emphasize the shared role of MTDH and SND1 in promoting cancer progression and highlight their potential as therapeutic targets." (PMID 41286067, 2025). "MTDH-induced autophagy activation in gastric cancer via AMPK/ATG5 signaling pathway and then enhanced 5-FU resistance in cancer cells." (PMID 38625581, 2024). "Metadherin (MTDH, also known as LYRIC and AEG-1) is a well-known oncogene that allows cancer cells to adhere closely to blood vessels to metastasis, moreover, MTDH protein promotes angiogenesis and confers chemoresistance." (PMID 38625581, 2024). "SND1 is an emerging drug target in cancer, and targeting protein–protein interaction sites in SND1, such as the interaction between SND1 and metadherin (MTDH), is an active area of research." (PMID 39169000, 2024). "Metadherin (MTDH), a newly discovered cancer-related antigen, promotes EMT, invasion and metastasis in a wide range of cancers, including breast and colon." (PMID 38023171, 2023). "We proposed MTDH as a novel factor that controls the RKIP transcription, which is essential for cancer progression." (PMID 37469399, 2023). "A growing body of evidence reveals the oncogenic functions of MTDH and PDCD10 in regulating cancer progression." (PMID 36071474, 2022). "Analysis of the site of expression revealed the existence of AKT1, MTDH, and NCOR2 genes in the colorectum and presence of TGFBR1 and MTDH in various cancer cell lines such as A-549 and HeLa." (PMID 36499586, 2022). "It targets certain oncogenes, such as AEG-1/MTDH, PDK1, YWHAZ/14-3-3ζ, YAP and JAK2, in multiple types of carcinomas." (PMID 35205648, 2022). "This study found that the positive correlation of MTDH expression and estimated EMT score is significant in various cancers." (PMID 34622157, 2021).
cancer (continued). "Therefore, the role of MTDH in cancer may connect with the function of m6A RNA methylation." (PMID 34622157, 2021). "In conclusion, we suggest that MTDH is a novel factor that controls the RKIP transcription, which is essential for cancer progression." (PMID 33802672, 2021). "MiRNA MIR497 with low expression silenced target genes BECN1, MTDH, and BCL2 to indulge cancer cell differentiation, angiogenesis, and metastasis." (PMID 33802957, 2021). "A previous study described its possible mechanism of action in cancer; HIF-1 can bind to the MTDH promoter and regulate MTDH expression." (PMID 33809336, 2021). "The oncogene Astrocyte elevated gene-1/Metadherin (AEG-1/MTDH) is overexpressed in a diverse array of cancers, and its overexpression promotes all the hallmarks of cancer, such as proliferation, invasion, metastasis, angiogenesis and chemoresistance." (PMID 33918653, 2021). "In summary, the present study fills a gap in the literature by demonstrating that MTDH is coexpressed and physically interacts with PTEN in resistant cancer cells." (PMID 32066429, 2020). "In cancer cells, RXR is sequestered in the cytoplasm by the co-repressor complex AEG-1/MTDH/LYRIC which decreases its transcriptional activity." (PMID 31771198, 2019). "Metadherin, also known as LYRIC/AEG1, plays a pivotal role in cancer and is reported to have many functions and subcellular localisations including mRNA binding in the endoplasmic reticulum (ER)." (PMID 31450747, 2019). "While conferring resistance to chemotherapy agents and radiotherapy, MTDH was found to promote the EMT, invasion, and metastasis in various types of cancers including breast cancer." (PMID 31527591, 2019). "In this study, we demonstrated that MTDH promotes CSC property of PDAC cells and prevents disseminating cancer cells from anoikis." (PMID 29029495, 2017). "It plays an important role in carcinogenesis, and overexpression of MTDH/AEG-1 can significantly enhance cell proliferation and anchorage-independent growth ability in a variety of cancers." (PMID 29073141, 2017). "Metadherin (MTDH) is an important oncogene, which is overexpressed in most cancers and responsible for apoptosis, metastasis, and poor patient survival." (PMID 27882943, 2016). "Astrocyte elevated gene-1 (AEG-1), also known as Metadherin (MTDH) and LYRIC, is an oncogene that is frequently overexpressed in various human cancers." (PMID 27793010, 2016). "Metadherin (MTDH), also known as astrocyte-elevated gene-1, was first cloned in 2002 and has been confirmed as an oncogene in numerous types of cancer by previous studies." (PMID 25684730, 2015). "MTDH also down-regulated many transcriptional inhibitor factors such as FOXO1 and FOXO3a and thus promoted malignant cancer cell proliferation." (PMID 26287185, 2015). "Due to the multiple functions of AEG-1/MTDH in drug resistance, AEG-1/MTDH is a viable target as an anticancer agent for a wide range of cancer types." (PMID 25009642, 2014). "Among the predicted mRNA targets of miR-22 are known cancer-related genes such as phosphatase and tensin homolog (PTEN), metadherin (MTDH), cyclin-dependent kinase 6 (CDK6), and laminin γ1 (LAMC1)." (PMID 24748979, 2014). "Current and future studies must focus on the translational aspects of AEG-1/MTDH, and on the understanding of AEG-1/MTDH function in physiological and pathological processes using transgenic and knockout mouse models in cancer." (PMID 25009642, 2014). "In summary, it has become apparent that AEG-1/MTDH is an important oncogene, which is overexpressed in numerous human cancer types." (PMID 25009642, 2014). "Forty-six out of our total 76 cases demonstrated high nuclear and cytoplasmic expression of AEG-1/MTDH, amongst which 30/30 carcinomas, 14/15 borderline ovarian tumours, and 1/31 benign tumours." (PMID 24963474, 2014).